JAKMIP2 (janus kinase and microtubule interacting protein 2)
Synonyms: JAMIP2; KIAA0555; NECC1
Tractability: PROTAC: ubiquitination databases record sites on it; its protein half-life has been measured.
Gene: Protein-coding gene on chromosome 5 (147,585,438 to 147,782,775, reverse strand). Ensembl gene ENSG00000176049.
Subcellular location: Golgi apparatus
Subcellular location (Human Protein Atlas): Golgi apparatus
Gene Ontology:
Molecular function: protein binding; kinase binding; microtubule binding
Cellular component: Golgi apparatus
Genetic constraint (gnomAD): Loss-of-function variants: 14 observed, 62.14 expected, observed/expected ratio (o/e) 0.23, 90% interval 0.15 to 0.35. The upper end of that interval is the gene's LOEUF score, 0.35, which puts it in group 1 of 6, group 1 being the genes least tolerant of losing a copy. Missense variants: 462 observed, 693.56 expected, observed/expected ratio (o/e) 0.67, 90% interval 0.62 to 0.72. Synonymous variants: 239 observed, 262.35 expected, observed/expected ratio (o/e) 0.91, 90% interval 0.82 to 1.01.
Homologues: Orthologues: chimpanzee JAKMIP2 (100% identical), macaque JAKMIP2 (99% identical), dog JAKMIP2 (99% identical), guinea pig JAKMIP2 (99% identical), mouse Jakmip2 (99% identical), rabbit JAKMIP2 (99% identical), rat Jakmip2 (98% identical), pig JAKMIP2 (97% identical), tropical clawed frog jakmip2 (89% identical), zebrafish jakmip2 (80% identical). Paralogues in human: JAKMIP1 (66% identical), JAKMIP3 (63% identical).
Diseases named in the same sentence as JAKMIP2 in open-access papers:
JAKMIP2 is named in the same sentence as 10 diseases in open-access papers, as found by Europe PMC text mining. Sharing a sentence is not in itself a finding about the gene and the disease. The quoted sentences say what the papers report.
prostate carcinoma (2 papers, 2025). A carcinoma that arises from epithelial cells of the prostate gland. "JAKMIP2 is associated with bone metastasis in prostate cancer and is a potential target for improving patient prognosis." (PMID 40746884, 2025). "miR - 135b, significantly downregulated in prostate cancer, promotes bone metastasis by enhancing the migration capacity of prostate cancer cells, with PLAG1, JAKMIP2, PDGFA, and VTI1B identified as potential mediators." (PMID 40837012, 2025).
COVID-19 (1 paper, 2025). A disease caused by infection with severe acute respiratory syndrome coronavirus 2. "In acutely infected COVID-19 patients, we found parallel expression of JAMMIP2 and HERV001 in a few samples, while in the PASC patients we found amplification of both JAKMIP2 and HERV001." (PMID 40642078, 2025).
immunodeficient diseases (1 paper, 2022). "The functional capacities of the highly expressed DEGs in the Chinese Simmental cattle mainly focused on inflammatory diseases (CXCL9 and FCRL1), immunodeficient diseases (ADM2, CCL5, and CAMKV), carcinoma (CXCL11, JAKMIP2, GZM, and DNAAF1), and GTP binding and GTPase activity (NUGGC)." (PMID 35495650, 2022).
pulmonary diseases (1 paper, 2020). "The other three genetic loci were rs188904275 in JAKMIP2 (p-value = 3.7×10−8), rs184670665 near IMPG1 (p-value = 2.4×10−10), and rs73586669 near OR4E1 (p-value = 2.4×10−8), with JAKMIP2 previously found to be associated with Body Mass Index (BMI) measurements and pulmonary diseases." (PMID 33075057, 2020).
JAKMIP2 also shares sentences with these, for which no sentence is quoted: bone metastasis (1 paper); carcinoma (1); colorectal cancer (1); leprosy (1); mammary tumors (1); tumor (1).